TCEAL9 (transcription elongation factor A like 9)
Description:
May be involved in transcriptional regulation.
Synonyms: WBP5; DKFZp313K1940; WEX6
Tractability: PROTAC: ubiquitination databases record sites on it.
Gene: Protein-coding gene on chromosome X (103,356,461 to 103,358,472, forward strand). Ensembl gene ENSG00000185222.
Subcellular location: Nucleus
Subcellular location (Human Protein Atlas): Nucleoli; Nucleoplasm
Gene Ontology:
Cellular component: nucleus
Homologues: Orthologues: chimpanzee TCEAL9 (100% identical), macaque TCEAL9 (99% identical), rabbit TCEAL9 (89% identical), pig TCEAL9 (88% identical), rat Tceal9 (81% identical), mouse Tceal9 (74% identical), guinea pig TCEAL9 (69% identical). Paralogues in human: TCEAL1 (45% identical), TCEAL8 (43% identical), TCEAL7 (41% identical), TCEAL4 (38% identical), TCEAL2 (36% identical), TCEAL5 (34% identical), TCEAL3 (32% identical), TCEAL6 (31% identical).
Diseases named in the same sentence as TCEAL9 in open-access papers:
TCEAL9 is named in the same sentence as 17 diseases in open-access papers, as found by Europe PMC text mining. Sharing a sentence is not in itself a finding about the gene and the disease. The quoted sentences say what the papers report.
colorectal cancer (3 papers, 2019 to 2025). A primary or metastatic malignant neoplasm that affects the colon or rectum. "WW domain binding protein 5 (WBP5), also known as Transcriptional Elongation Factor A like 9 (TCEAL9) has been proposed as a candidate oncogene for human colorectal cancers with microsatellite instability and as a predictive indicator of small cell lung cancers." (PMID 32103106, 2020).
autism (1 paper, 2020). Persistent deficits in social interaction and communication and interaction as well as a markedly restricted repertoire of activity and interest as well as repetitive patterns of behavior. "Also, a small 252-kb duplication spanning BEX3, TCEAL4, TCEAL9, and RAB40A has been reported in a patient with autism (Decipher database, ID: 290829)." (PMID 33100228, 2020).
viral infection (1 paper, 2021). "Several differentially expressed genes between the two trajectories (CTSG, PRC1, DEFA4, KIF15, TCEAL9, HMMR, CEP55, and AZU1) were overexpressed in patients with severe viral infection, but not in those with non-severe viral infection compared to HCs." (PMID 33765435, 2021).
cancer (3 papers, 2020 to 2025). A tumor composed of atypical neoplastic, often pleomorphic cells that invade other tissues. "The majority were localized to cluster lungH1 and expressed lower levels of metastatic cancer cell markers (ALDH3A1, VIM, TCEAL9)." (PMID 34579762, 2021).
TCEAL9 also shares sentences with these, for which no sentence is quoted: tumor (4 papers); acute myeloid leukaemia (3); gastric cancer (2); coronary artery disease (1); head and neck cancer (1); head and neck squamous cell carcinoma (1); leukaemia (1); lymph node metastasis (1); myeloid leukaemias (1); ovarian carcinoma (1); Papillary Thyroid Carcinoma (1); small cell lung carcinoma (1); thyroid cancer (1).